STAU2 (staufen double-stranded RNA binding protein 2)
Description:
RNA-binding protein required for the microtubule-dependent transport of neuronal RNA from the cell body to the dendrite. As protein synthesis occurs within the dendrite, the localization of specific mRNAs to dendrites may be a prerequisite for neurite outgrowth and plasticity at sites distant from the cell body (By similarity).
Synonyms: 39K2; 39K3
Tractability: Antibody: its Gene Ontology location is reachable by antibodies, with medium confidence. PROTAC: ubiquitination databases record sites on it; its protein half-life has been measured.
Gene: Protein-coding gene on chromosome 8 (73,420,369 to 73,747,708, reverse strand). Ensembl gene ENSG00000040341.
Subcellular location: Cytoplasm; Nucleus; Nucleus, nucleolus; Endoplasmic reticulum
Subcellular location (Human Protein Atlas): Nucleoplasm; Cytosol
Gene Ontology:
Molecular function: double-stranded RNA binding; protein binding; RNA binding; mRNA binding; Hsp70 protein binding; kinesin binding; mitogen-activated protein kinase binding; ribosome binding
Biological process: anterograde dendritic transport of messenger ribonucleoprotein complex; germ cell development; intracellular mRNA localization; protein localization to synapse; cellular response to oxidative stress; eye morphogenesis; positive regulation of dendritic spine morphogenesis; positive regulation of long-term synaptic depression; positive regulation of synapse assembly; regulation of actin cytoskeleton organization; regulation of filopodium assembly
Cellular component: cytosol; membrane; nucleoplasm; cytoplasmic stress granule; neuron projection; neuronal cell body; plasma membrane; axon; cytoplasm; dendrite; dendrite cytoplasm; dendritic shaft; endoplasmic reticulum; glutamatergic synapse; nuclear membrane; nucleolus; nucleus; postsynapse; protein-containing complex
Genetic constraint (gnomAD): Loss-of-function variants: 18 observed, 55.75 expected, observed/expected ratio (o/e) 0.32, 90% interval 0.22 to 0.48. The upper end of that interval is the gene's LOEUF score, 0.48, which puts it in group 2 of 6, group 1 being the genes least tolerant of losing a copy. Missense variants: 515 observed, 644.73 expected, observed/expected ratio (o/e) 0.8, 90% interval 0.74 to 0.86. Synonymous variants: 219 observed, 220.77 expected, observed/expected ratio (o/e) 0.99, 90% interval 0.89 to 1.11.
Homologues: Orthologues: rabbit STAU2 (97% identical), guinea pig STAU2 (96% identical), pig STAU2 (96% identical), mouse Stau2 (94% identical), rat Stau2 (94% identical), chimpanzee STAU2 (93% identical), dog STAU2 (92% identical), macaque STAU2 (91% identical), zebrafish stau2 (74% identical), tropical clawed frog stau2 (73% identical), Drosophila melanogaster loqs (10% identical), Drosophila melanogaster Zn72D (7% identical), and 3 more. Paralogues in human: STAU1 (42% identical), ADAR (18% identical), ADARB1 (17% identical), ADARB2 (15% identical), ADAD1 (12% identical), TARBP2 (12% identical), ADAD2 (10% identical), PRKRA (9% identical), ZFR2 (9% identical), ADAT1 (8% identical), ILF3 (7% identical), ILF2 (7% identical), and 2 more.
Diseases named in the same sentence as STAU2 in open-access papers:
STAU2 is named in the same sentence as 21 diseases in open-access papers, as found by Europe PMC text mining. Sharing a sentence is not in itself a finding about the gene and the disease. The quoted sentences say what the papers report.
myeloid leukemia (3 papers, 2022 to 2025). A clonal proliferation of myeloid cells and their precursors in the bone marrow, peripheral blood, and spleen. "The important roles of STAU2 in myeloid leukemia support its potential significance in cancer therapy." (PMID 40539383, 2025). "In a recent report, RNA-binding proteins (RBPs) were identified as critical regulators of myeloid leukemia, with extensive studies focusing on the RBP staufen 2 (Stau2)." (PMID 36642223, 2023).
breast carcinoma (2 papers, 2021 to 2024). "The upregulation of STAU2, observed in T and B cells in human breast cancer patients may promote tumor growth through the RNA transport process of various inflammatory cytokine molecules suggesting its potential as a novel diagnostic biomarker for human breast cancer screening." (PMID 38951817, 2024). "The specific upregulation of STAU2 in WBCs in breast cancer makes the protein a potential target for breast cancer immunotherapy." (PMID 33441653, 2021). "Second, the average fluorescence intensity of anti-STAU2 in breast cancer patients was significantly increased compared with that in healthy females (p < 0.0001)." (PMID 33441653, 2021). "Therefore, the STAU2 protein in T and B cells represents a promising breast cancer marker for improving breast cancer screening programmes." (PMID 33441653, 2021). "Our study identified STAU2 protein as a novel breast cancer marker in T and B cells." (PMID 33441653, 2021). "The fluorescent signals from anti-STAU2 were indicated in WBCs from breast cancer patients." (PMID 33441653, 2021). "Therefore, STAU2-positive cells were exclusively identified in breast cancer T and B cells (p = 0.0005)." (PMID 33441653, 2021). "Five proteins (LMAN1, AZI2, STAU2, MMP9 and PLOD1) from a systemic analysis of a variety of array data of breast cancer patients were subjected to immunofluorescence staining to evaluate the presence of fixed WBCs on 96-well plates from 363 healthy females and 358 female breast cancer patients." (PMID 33441653, 2021). "The average fluorescence intensity of anti-STAU2 was not significantly different among WBCs obtained from normal females with 1 to 3 mammograms, but an increasing trend was noted from early-stage to late-stage breast cancer patients (p = 0.0008)." (PMID 33441653, 2021).
gastric cancer (2 papers, 2012 to 2021). A primary or metastatic malignant neoplasm involving the stomach. "In MSI-positive GCs, ACVR2A, RPL22, LMAN1, and STAU2 were observed to have recurrent single base thymine deletions in poly(T) regions and this was confirmed in a screen of an additional 94 gastric cancer/normal paired samples (9 MSI-positive)." (PMID 23237666, 2012).
pancreatic adenocarcinoma (2 papers, 2022 to 2024). "Recently, a noteworthy finding has emerged, underscoring the indispensable regulatory role of STAU2 in pancreatic adenocarcinoma, and DDX3X was identified as its target gene." (PMID 38316768, 2024).
pancreatic cancer (2 papers, 2022 to 2025). "The xenograft model based on PANC‐1 cells showed that STAU2 overexpression significantly promoted the proliferation and metastasis of pancreatic cancer cells in vivo." (PMID 40539383, 2025). "Rescue experiments overexpressing PALLD in shSTAU2 cell lines validated the regulatory role of the STAU2‐PALLD‐EMT axis in pancreatic cancer cell migration, invasion, and EMT pathway expression." (PMID 40539383, 2025). "In summary, our work revealed and comprehensively validated the promoting role of STAU2‐PALLD axis in the progression and metastasis of pancreatic cancer, suggesting that STAU2 as a novel drug target for therapeutic intervention." (PMID 40539383, 2025). "The present findings highlight STAU2 as a pivotal molecule in EMT‐mediated metastasis in pancreatic cancer." (PMID 40539383, 2025). "STAU2 silencing significantly inhibited the growth of pancreatic cancer cells, with an inhibition rate of 53.26% in the BxPC3 xenograft model." (PMID 40539383, 2025). "Migration and invasion assay results showed that STAU2 overexpression significantly promoted pancreatic cancer metastasis at cellular levels." (PMID 40539383, 2025). "In summary, our study demonstrated that the STAU2‐PALLD axis promoted the progression and metastasis of pancreatic cancer, and developed STAU2‐ASO as the first inhibitor targeting STAU2‐PALLD axis." (PMID 40539383, 2025). "In summary, STAU2‐ASO exhibited potent anti‐tumor activity and significantly inhibited the proliferation and metastasis of pancreatic cancer cells in vitro." (PMID 40539383, 2025). "We also analyzed STAU2 expression in pancreatic cancer patients without and with radiation therapy and found that pancreatic cancer patients who received radiation therapy had significantly lower STAU2 expression than those who did not." (PMID 35892886, 2022). "Moreover, STAU2‐ASO was developed as the first inhibitor targeting STAU2, demonstrating anti‐tumor activity both in vitro and in vivo and providing a promising novel therapeutic strategy for pancreatic cancer treatment." (PMID 40539383, 2025).
spinocerebellar ataxia type 2 (2 papers, 2025). A subtype of type I autosomal dominant cerebellar ataxia (ADCA type I) characterized by truncal ataxia, dysarthria, slowed saccades and less commonly ophthalmoparesis and chorea. "STAU2 protein, but not mRNA, was overabundant in spinocerebellar ataxia type 2 (SCA2), ALS/frontotemporal dementia patient fibroblasts, ALS patient spinal cord tissues, and in central nervous system tissues from SCA2 and ALS animal models." (PMID 39955058, 2025).
cerebellar ataxia (1 paper, 2019). A neurological syndrome characterized by clumsy and uncoordinated movement of the limbs, trunk, and cranial muscles. "A better understanding of the involvement of Stau2 in GluD2-dependent synapse formation could therefore provide new therapeutic options for cerebellar ataxia and similar disorders." (PMID 30979012, 2019).
colorectal cancer (1 paper, 2021). A primary or metastatic malignant neoplasm that affects the colon or rectum. "In addition, the downregulation of STAU2 in HCT116 colorectal cancer cells increases DNA damage and promotes apoptosis." (PMID 33968009, 2021).
frontotemporal dementia (1 paper, 2025). Frontotemporal dementia (FTD) comprises a group of neurodegenerative disorders, characterized by progressive changes in behavior, executive dysfunction and language impairment, as a result of degeneration of the medial prefrontal and frontoinsular cortices. "In this study, we show that STAU2 steady-state levels are increased in SCA2 and ALS/frontotemporal dementia (FTD)-C9ORF72 cellular and mouse models as well as in spinal cord tissues from patients with ALS." (PMID 39955058, 2025).
HIV-1 infection (1 paper, 2021). The type species of lentivirus and the etiologic agent of acquired immunodeficiency syndrome (AIDS). "Although a similar regulatory pathway was not reported in STAU1, its homolog STAU2 could act as a positive regulator that interacts with HIV-1 Rev to promote HIV-1 infection." (PMID 34452292, 2021).
influenza (1 paper, 2021). An acute viral infection of the respiratory tract, occurring in isolated cases, in epidemics, or in pandemics; it is caused by serologically different strains of viruses (influenzaviruses) designated A, B, and C, has a 3-day incubation period, and usually lasts for 3 to 10 days. "Thus, we hypothesize that the interaction between NS1 and STAU2 might be a conserved association in different influenza strains." (PMID 33968009, 2021).
neuroblastoma (1 paper, 2013). Neuroblastoma (NB) is the most common solid, extracranial childhood tumor. "Lastly, Sepw1 mRNA associates with Stau2 in SH-SY5Y neuroblastoma cells." (PMID 24392277, 2013). "In addition to Stau2, DJ-1/Park7 has been experimentally demonstrated to coimmunoprecipitate with Sepw1 mRNA in M17 human neuroblastoma cells and human brain tissue." (PMID 24392277, 2013).
pancreatic ductal adenocarcinoma (1 paper, 2025). An infiltrating adenocarcinoma that arises from the epithelial cells of the pancreas. "This study identifies STAU2 as an oncogenic RNA‐binding protein (RBP) with elevated expression in pancreatic ductal adenocarcinoma (PDAC), where its high levels are significantly correlated with metastatic progression." (PMID 40539383, 2025).
Sepsis (1 paper, 2024). Sepsis is defined as life-threatening organ dysfunction caused by a dysregulated host response to infection. "According to the qPCR results, we validated circRNAs such as hsa-circ-0008285 (exons of CDYL) and hsa-circ-0001811 (exons of STAU2) as potential biomarkers for severe sepsis." (PMID 39071490, 2024).
cancer (8 papers, 2021 to 2025). A tumor composed of atypical neoplastic, often pleomorphic cells that invade other tissues. "All these findings indicate that STAU2 is a novel prognostic and diagnostic biomarker for PAAD, which highlights the attractive potential of RBPs in cancer therapy and drug development." (PMID 35892886, 2022). "STAU2 is also linked to the DNA damage response and the apoptotic pathway since STAU2 depletion causes an accumulation of DNA damage and facilitates apoptosis in the HCT116 cancer cell line." (PMID 33663378, 2021). "The YAP1/ABHD11‐AS1/STAU2/ZYX/p‐YAP1 pathway is a useful entry point for exploration of specific mechanisms of mechanical signal conduction from the ECM in ICC cells and their impact on cancer progression." (PMID 39703167, 2025). "Next, we used the YAP1/ABHD11‐AS1/STAU2/ZYX/p‐YAP1 signaling pathway as the entry point to explore specific mechanisms via which mechanical signals are conducted from the ECM in ICC cells and their impact on the progression of cancer." (PMID 39703167, 2025). "We used the YAP1/ABHD11‐AS1/STAU2/ZYX/p‐YAP1 signaling pathway as the entry point to explore the specific mechanisms involved in conduction of mechanical signals from the ECM in ICC cells and their impact on progression of cancer." (PMID 39703167, 2025). "In contrast, Rbfox1, FMRP, and Stau2 were either not enriched in cancer cells or showed reduced expression compared to Pum2." (PMID 34445704, 2021). "We show that STAU2 depletion accelerates cell cycle progression in non-transformed cells but not in cancer cells." (PMID 33663378, 2021). "The upregulated levels of STAU2 protein only in T and B cells might be related to the RNA transport mechanism to produce various inflammatory cytokine (IL-10, TNF-α) molecules that are required to promote tumour growth in the cancer microenvironment." (PMID 33441653, 2021). "Moreover, we compared cancer cell expression with mRNA levels in healthy neural progenitor cells and mature neurons for essential neuronal RBPs such as FMRP, RNA-binding protein fox-1 (Rbfox1), Staufen2 (Stau2), and Pum2." (PMID 34445704, 2021). "To determine if STAU2 is a downstream factor in the CHK1 pathway as suggested by the BioID2 assay, we treated the non-transformed hTERT-RPE1 and the cancer HCT116 cells with the CHK1 inhibitor PF-477736 (PF47) for 8 h." (PMID 33663378, 2021).
tumor (7 papers, 2017 to 2025). "In the present study, bioinformatics analysis of tumor genome databases and immunofluorescence staining of clinical tissues demonstrated that STAU2 overexpression was closely associated with PDAC metastasis and correlated with poor overall survival (OS)." (PMID 40539383, 2025). "In recently published research on PDAC, high STAU2 expression has been linked to tumor progression, immune evasion, and chemotherapy resistance, and experimental studies indicated that STAU2 promoted aggressive tumor behavior." (PMID 41465326, 2025). "Collectively, these results suggested that STAU2 is an important factor in promoting the proliferation and metastasis of tumor cells in vitro and in vivo." (PMID 40539383, 2025). "Our study findings highlight the significant potential of STAU2 blockade in tumor progression and metastasis, offering a promising perspective and target for the development of innovative anticancer therapies." (PMID 40539383, 2025). "Tumor growth in the STAU2 knockdown group was significantly reduced compared to that in the control group, demonstrating an inhibition rate of 30.66%." (PMID 40539383, 2025). "To further investigate the effect of STAU2 on different functional T cells, we analyzed the correlation between the expression of STAU2 and tumor immune infiltration cells (TIICs) using the xCell algorithm in the PAAD dataset." (PMID 35892886, 2022). "We observed that silencing STAU2 not only inhibited cell proliferation, colony formation, and metastasis but also induced tumor apoptosis." (PMID 35892886, 2022). "Our data indicate that STAU2 is modified during mitosis in both untransformed and transformed cell lines derived from two different tissues, normal retina and tumor from cervix, respectively." (PMID 28705199, 2017). "The tumor‐promoting role of STAU2 in PDAC highlights its potential as a novel therapeutic target." (PMID 40539383, 2025). "The number of migrating and invading tumor cells was significantly reduced after STAU2 knockdown." (PMID 40539383, 2025). "Notably, STAU2 knockdown resulted in significant tumor growth and metastasis suppression, mediated via down‐regulation of the EMT signaling pathway both in vitro and in vivo." (PMID 40539383, 2025). "The results revealed a statistically significant STAU2 up‐regulation in tumor samples." (PMID 40539383, 2025). "Furthermore, several recent articles have reported that STAU2 emerged as a critical mediator in tumor progression." (PMID 35892886, 2022). "In addition, STAU2‐ASO treatment led to a marked STAU2 expression down‐regulation and the EMT pathway suppression in tumor tissues, confirming its potent anti‐metastatic efficacy in PDAC." (PMID 40539383, 2025). "Oncogenic transformation may also explain why tumor cells are not affected by STAU2 depletion." (PMID 33663378, 2021).
infection (1 paper, 2017). The state of being infected such as from the introduction of a foreign agent such as serum, vaccine, antigenic substance or organism. "In both cell lines, bands recognized by the STAU2 antibody disappeared as a consequence of infection with shRNA against STAU2, authenticating the shifted bands as STAU2 proteins." (PMID 28705199, 2017).
neurodegenerative disease (1 paper, 2025). A disorder of the central nervous system characterized by gradual and progressive loss of neural tissue and neurologic function. "We now demonstrate that exogenous expression of miR-217 significantly reduced STAU2 and mTOR levels in cellular models of neurodegenerative disease." (PMID 39955058, 2025).
STAU2 also shares sentences with these, for which no sentence is quoted: liver cancer (1 paper); ovarian carcinoma (1); stomach cancer (1).